CRP (C-reactive protein)
Diseases named in the same sentence as CRP in open-access papers (continued):
Sharing a sentence is not in itself a finding about the gene and the disease.
acute coronary syndrome (continued). "In acute coronary syndrome, MMP and CRP are correlated, and CRP seems to induce local MMP-9 secretion." (PMID 29929486, 2018). "In previous studies, CRP, WBCs, neutrophils and NLR were reported to be related to acute coronary syndromes and can be considered as prognostic markers." (PMID 30501029, 2018). "The concentration of these C-reactive protein, myeloperoxidase, soluble CD40 ligand and placental growth factor were significantly increased in acute coronary syndrome patients." (PMID 26576922, 2015). "This study aimed to investigate the differences in level of several biomarkers, i.e. C-reactive protein, myeloperoxidase, soluble CD40 ligand and placental growth factor, between acute coronary syndrome and chronic stable angina patients." (PMID 26576922, 2015). "The circulating inflammatory markers such as C-reactive protein (CRP), serum amyloid A (SAA), interleukin (IL)-6 and IL-1 receptor commonly accompany with acute coronary syndromes." (PMID 26354089, 2015). "In patients with acute coronary syndrome, statin drug therapy lowered both plasma LDL and CRP levels and provided early clinical benefits." (PMID 23950953, 2013). "Our analysis of the MIRACL study shows a strong relationship between early levels of CRP and the closely related markers of IL‐6 and SAA with death following an acute coronary syndrome." (PMID 23525424, 2013). "The effect of other acute phase reactants such as TNF, CRP and IL6 in prognosis of acute coronary syndromes is also known." (PMID 22811936, 2012). "And finally, when the investigators examined HSP27 levels in plasma, they found that in patients with acute coronary syndrome, levels of HSP27 were increased and found to correlate with levels of HSP70, C-reactive protein, and CD40L." (PMID 23304456, 2012). "While the average CRP level in patients was 2.86 mg/L (CRP concentration of 1,278 CAD patients with > 50% stenosis with acute coronary syndromes, and unstable angina pectoris were disregarded) this value was 2.55 mg/L in controls." (PMID 19480687, 2009). "Currently, the American College of Cardiology/American Heart Association and European Society of Cardiology do not endorse use of CRP, H-FABP, or sST2 for risk stratification or prediction in acute coronary syndrome." (PMID 41010838, 2025). "Serum levels of C-reactive protein dropped after vitamin D supplementation in patients with non-ST-elevation acute coronary syndrome (p = 0.028 *), demonstrating its beneficial effects." (PMID 37259407, 2023). "The present study aimed to understand the association between increased levels of highly sensitive CRP (hs-CRP) and non-arrhythmic ECG changes and electrocardiographic abnormalities in patients with the acute coronary syndrome." (PMID 36741499, 2023). "There is no published data on the impact of preexisting AF on hs-CRP plasma levels in the patients with acute coronary syndromes." (PMID 29118378, 2017). "The aim of this study was to investigate the correlation between the severity of coronary artery lesions in patients with acute coronary syndromes (ACS) and levels of estrogen, high-sensitivity C-reactive protein (hs-CRP) and matrix metalloproteinase-9 (MMP-9)." (PMID 24940407, 2014). "The current study indicates that PAPP-A expression in human PBMCs may be regulated by CRP and TNF-α through the NF-κB pathway, a mechanism that may play a critical role in increases in serum PAPP-A levels during acute coronary syndrome (ACS)." (PMID 22997483, 2012). "Furthermore, HSP70 has been found to be up-regulated in the proteome of monocytes in acute coronary syndrome (ACS), a disease in which circulating CRP levels are increased as well." (PMID 21219634, 2011). "In LURIC CRP is increased in CAD patients compared to healthy controls but the increase is only significant for patients with acute coronary syndromes, not for patients with stable CAD." (PMID 21062467, 2010).
acute coronary syndrome (continued). "Neither did we find, in our study of non-lupus patients with acute coronary syndrome, any raised anti-CRP levels compared with the age-matched controls that were anamnestically healthy and without medication." (PMID 20003354, 2009). "However, CRP is not helpful for the diagnosis and treatment of acute coronary syndrome patients, but its measurement after ACS and PCI identifies those patients at risk for further complications and worse prognosis." (PMID 41226718, 2025). "CRP also stimulates the release of a soluble isoform of LOX-1, both classically activated and derived from peripheral blood mononuclear cells macrophages, in people with acute coronary syndrome and possibly smokers in a process involving FcγRIIa, TNF, and ROS synthesis." (PMID 37873776, 2023). "In studies of acute coronary syndrome (ACS), colchicine has been shown to prevent NLPR3 inflammasome-induced caspase-1 activation, leading to decreased levels of interleukin IL-1b, IL-18, and IL-6 and CRP and a reduction in mortality from major cardiovascular events." (PMID 33133323, 2020). "Administration of calcitriol in patients with non-ST-segment elevation acute coronary syndromes undergoing elective PCI can attenuate the increase in serum inflammatory biomarkers in the serum (hs-CRP and hs-IL-6) and thus decrease the inflammatory reaction caused by PCI." (PMID 32802107, 2019). "The relationship between acute coronary syndrome (ACS) and local and systemicinflammation, including accumulation of macrophages in atherosclerotic plaquesand upregulation of blood cytokines (e.g., C-reactive protein (CRP)), has beenknown for more than 100 years." (PMID 27437144, 2016). "Moreover, in those with acute coronary syndrome (ACS), sAXL levels are significantly elevated compared to healthy controls and show a positive correlation with inflammatory markers such as high-sensitivity C-reactive protein (hs-CRP) and tumor necrosis factor-alpha (TNF-α)." (PMID 40933570, 2025). "This study aimed to investigate the relationship between increased levels of highly sensitive CRP (hs-CRP) and non-arrhythmic ECG changes and electrocardiographic abnormalities in patients with acute coronary syndrome." (PMID 36741499, 2023). "On univariate analyses, baseline CRP (P=0.006), SAA (P=0.012), and IL‐6 (P<0.001) were related to death, but not to recurrent nonfatal acute coronary syndromes." (PMID 23525424, 2013). "Increased levels of circulating miR-183-5p were also detected in patients with acute coronary syndrome (ACS) and non-ST-segment elevation myocardial infarction (NSTEMI), with the observation that serum miR-183-5p levels positively correlated with the Gensini score and hs-CRP." (PMID 41009624, 2025).
asthma (236 papers, 2007 to 2026). "While CRP has been extensively studied, it lacks specificity as an asthma predictor, as elevated CRP levels are associated with a wide range of inflammatory conditions." (PMID 40546825, 2025). "Conversely, depressive symptoms—particularly when co-occurring with chronic conditions like asthma—were associated with elevated CRP." (PMID 40514590, 2025). "Both CRP and hs-CRP have shown diagnostic value for asthma, while SAA1 has also been linked to lung diseases." (PMID 40915180, 2025). "In men, asthma and elevated hs-Troponin T levels increased the risk of death during the pandemic, while elevated hs-CRP and NT-proBNP levels were associated with higher risk in both periods." (PMID 39774287, 2025). "High CRP levels were observed in patients suffering from comorbid asthma and sleep apnea are due to the enhanced cardiovascular risk in these patients to warrant improved cardiovascular surveillance among clinic patients." (PMID 40662069, 2025). "CRP levels above 5 mg/L are associated with asthma flares, poor asthma control, and higher cardiovascular events." (PMID 40662069, 2025). "Increased CRP levels are associated with increased asthma severity, higher frequency of exacerbations, and airway changes that lead to reduced lung function." (PMID 40662069, 2025). "In the univariable models, female sex, Black race, BMI, and CRP were positively associated with the odds of high IL-6 asthma, while FEV1 was negatively associated with the odds of high IL-6." (PMID 39714726, 2025). "For instance, CRP levels are elevated in asthma patients but are also associated with other inflammatory conditions and do not correlate well with localized airway inflammation, making CRP levels a non-specific marker for asthma severity or control." (PMID 40872499, 2025). "Other aspects of inflammation like CRP that also rises in asthma is directly associated with airflow resistance and diminished lung functionality in order to grade the asthmatic condition." (PMID 40662069, 2025). "In our study the top 5 characteristics sorted by gain were concordant with current literature: there is strong epidemiological evidence that diet, eosinophils, hip circumference, standing height and C-reactive protein levels are associated with asthma." (PMID 37992024, 2023). "Within this population, we have previously observed associations between maternal CRP levels with lower maternal education, higher gravidity, uncontrolled asthma, unhealthy diet, prior premature births and risk of preterm birth." (PMID 36499584, 2022). "In fact, activation of NF-κB can affect asthma through inflammatory protein regulation, and the increased level of high sensitivity CRP is also associated with airflow obstruction and airway inflammation." (PMID 34750467, 2021). "Serum CRP levels, as determined by high‐sensitivity CRP assays, have been found to be significantly elevated in asthma patients as compared to healthy controls, suggesting an association between plasma CRP levels and the severity of asthma." (PMID 32246830, 2020). "Systemic inflammation is also a feature of asthma, with circulating C-reactive protein (CRP) levels shown to be elevated in people with asthma, which is associated with poorer lung function and more severe airway inflammation." (PMID 31892115, 2019). "IL-6, C-reactive protein (CRP) and other inflammatory markers are associated with asthma and eczema." (PMID 27476619, 2017). "Using data from ALSPAC we assessed associations between serum CRP and IL-6, aged 9 years, atopic conditions (asthma and eczema) before age 10 years, and lifetime experience of hypomanic symptoms assessed at 22 years." (PMID 27476619, 2017). "Increased serum high sensitive C-reactive protein (hs-CRP) in asthma and its association with disease severity has been investigated in many studies." (PMID 26958331, 2016).
asthma (continued). "This study has limitations regarding study design which is cross-sectional and indicates an association between high serum hs-CRP level and asthma." (PMID 26958331, 2016). "When single factors were assessed, CRP levels were positively associated with endotoxin (p = 0.016) and asthma (p = 0.011)." (PMID 26792395, 2016). "Regarding the association between serum CRP and future cardiovascular events, these findings highlight serum hs-CRP measurement in asthma not only in predicting asthma control but also for future development of cardiovascular morbidities." (PMID 26958331, 2016). "It is known from recent studies that CRP is elevated in asthma and that high CRP is associated with respiratory impairment or bronchial hyperresponsiveness." (PMID 23565268, 2013). "Systemic inflammation in asthma causes an acute phase response, as it was shown by increased level of C-reactive protein (CRP) related to total immunglobulin (Ig)E levels or respiratory symptoms of asthma." (PMID 23565268, 2013). "In addition, elevated CRP levels are associated with reduced responsiveness to treatment and more significant declines in lung function among asthma patients." (PMID 40259948, 2025). "In addition, CRP is strongly associated with the frequency and severity of asthma attacks, and serum CRP levels are negatively correlated with the severity of acute asthma attacks." (PMID 40259948, 2025). "Moreover, CRP has also been indicated to have positive association with airway changes and poor lung function in asthma patients which make it a good indicator of asthma progression." (PMID 40662069, 2025). "Human GWAS is remarkably concordant with these observations and identify associations between SNPs in the genes coding for cohesin with leukocyte traits, C-reactive protein and canonical autoimmune conditions as RA, MS, asthma and HLA-B27 associated inflammatory conditions." (PMID 35222432, 2022). "In addition, it was associated an increase in both baPWV and CRP in asthma patients compared with control subjects." (PMID 33608061, 2021). "Evidence reported an association of CRP levels with the severity of asthma and COPD." (PMID 34314447, 2021). "However, a few studies have associated HNL and CRP to airway inflammation and to the prediction of asthma status, but these markers seem to be resistant to corticosteroid treatment." (PMID 30834110, 2019). "Also we reported that saffron in asthmatic patients reduced anti-heat shock protein 70 (as a novel risk factor for asthma severity) and high sensitive-c reactive protein and also improved the lung function (assessed via spirometry test)." (PMID 30795753, 2019). "In addition, this marker has been reported to be associated with levels of fibrinogen and C-reactive protein in blood as well as asthma and pulmonary function." (PMID 25340798, 2014). "Moreover, in patients undergoing angioplasty, nano‐curcumin at the same dose caused a significant decrease in hs‐CRP levels.Besides, the systematic review had shown that curcumin improved the severity of inflammation including asthma, inflammatory bowel disease, and juvenile idiopathic arthritis." (PMID 37324924, 2023). "Asthma patients showed greater decreases in CRP and TNF-α compared to infection or COPD groups, indicating that disease type has a substantial impact on treatment effects for inflammatory markers." (PMID 41555409, 2026). "Studies have shown that airway epithelial cells and inflammatory cells in asthma patients can produce CRP locally." (PMID 40259948, 2025). "In asthma patients before the vaccination, the IL-6 level is directly correlated with the level of serum CRP (r = 0.68; p <0.05." (PMID 39937802, 2025).
asthma (continued). "Regarding asthma, sleep apnea, and other chronic diseases, the rise in CRP levels is attributed to chronic, low-grade inflammation that fosters pathophysiological processes and comorbidities." (PMID 40662069, 2025). "Examining FeNO and CRP levels helps clinicians understand the intricate interplay between asthma and sleep apnea, making asthma more manageable, reducing exacerbations, and minimizing the impact of sleep apnea on patients." (PMID 40662069, 2025). "Patients with OSA often present with systemic inflammatory responses which raise CRP amounts although this increase stems indirectly from combined pathophysiological influences of OSA together with asthma." (PMID 40662069, 2025). "CRP and FeNO are useful parameters for assessing inflammation of both asthma and sleep apnea, their levels should be monitored on a coherent basis." (PMID 40662069, 2025). "Biomarkers like FeNO and CRP measure inflammation in asthma and sleep apnea comorbidity, determining airway inflammation and eosinophilic response." (PMID 40662069, 2025). "CRP dynamics in asthma and COPD patients and healthy volunteers before and after vaccination against influenza (reference value: Up to 8 mg/L)." (PMID 39937802, 2025). "Where symptoms of asthma are compounded by sleep apnea, CRP can therefore offer supplementary details about objective inflammation." (PMID 40662069, 2025). "As a result, CRP has emerged as one of the most crucial indices for assessing the condition and prognosis of asthma." (PMID 40259948, 2025). "The level of CRP exceeded the conditional norm (up to 8 mg/L) in all study periods in asthma and COPD patients." (PMID 39937802, 2025). "High baseline CRP levels in the metformin and placebo groups can be attributed to MetS and asthma attacks." (PMID 40787554, 2025). "While a plethora of information exists on FeNO and CRP in asthma and SAs separately, comparatively limited data has been published on the association of these two indices in patients with both BA and OSA." (PMID 40662069, 2025). "Studies have demonstrated that in asthma, CRP levels increase with disease severity, with an increase in asthma exacerbations and systemic inflammation." (PMID 40662069, 2025). "CRP as a marker for systemic inflammation explain increased levels of CRP in patients with both asthma and sleep apnea as the consequence of systematic inflammation." (PMID 40662069, 2025). "This section will be devoted to discussing effectiveness and applicability of FeNO and CRP for clinical practice of patients with asthma and OSA." (PMID 40662069, 2025). "FeNO and CRP have been investigated separately to asthma and sleep apnea but a few authors describe how both can be related or linked regarding the patients with both pathologies." (PMID 40662069, 2025). "In, contrast, CRP is a measure of systemic inflammation that is usually high in both forms of asthma." (PMID 40662069, 2025). "Although several biomarkers such as CRP, eosinophil counts, and fractional exhaled nitric oxide (FeNO) have been used to assess asthma-related inflammation, each has notable limitations." (PMID 40546825, 2025). "Biomarkers like FeNO and CRP should be routinely checked in patients with concurrent asthma and sleep apnea to assess disease outcomes, compare therapeutic approaches, and identify patients with increased risk factors." (PMID 40662069, 2025). "Elevated mean CRP levels have been reported in those patients with both asthma and sleep apnea than in subjects with only sleep apnea." (PMID 40662069, 2025). "Understanding the relationship between FeNO, CRP, and the comorbidity of asthma and sleep apnea has significant clinical implications." (PMID 40662069, 2025). "Increased CRP is found in both asthma and sleep apnea, with SH having a direct positive correlation with CRP." (PMID 40662069, 2025). "On the other hand, CRP is a systemic marker of inflammation that can be elevated in any type of disease, such as asthma and/or sleep apnea syndrome." (PMID 40662069, 2025).